LCAT (lecithin-cholesterol acyltransferase)
Diseases named in the same sentence as LCAT in open-access papers (continued):
Sharing a sentence is not in itself a finding about the gene and the disease.
diabetes (continued). "Model 4: adjusted for age; sex; diabetes status; use of metformin, sulfonylurea and antihypertensive medication; LCAT activity (A) or CETP mass (B); non-HDL cholesterol; and triglycerides." (PMID 30744100, 2019). "Similarly, no diabetes-induced changes were observed in the activity of LCAT nor the pro-inflammatory index of HDL." (PMID 32235466, 2020). "Among lipid markers, non-HDL-C, TG concentrations, and LCAT activity were significantly higher in newly diagnosed diabetes subjects, whereas HDL-C was significantly lower in newly diagnosed diabetes subjects." (PMID 30055622, 2018). "Given the relevance of PLTP and LCAT for altered HDL remodelling and triglyceride metabolism in diabetes, we decided to include both diabetic and non-diabetic subjects in the present study." (PMID 27581838, 2016).
Sepsis (12 papers, 2010 to 2024). Sepsis is defined as life-threatening organ dysfunction caused by a dysregulated host response to infection. "In our previous study, we found that reduced LCAT activity due to increased oxidative stress is a cause of reduced cholesterol levels, and albumin is a transport carrier of cholesterol and other molecules, likely affecting the fluctuation in fatty acid and outcomes in sepsis." (PMID 36832250, 2023). "LCAT activity was negatively correlated with CRP in sepsis, consistent with the positive correlation between FC and CRP." (PMID 39311203, 2024). "The LCAT substrate turnover, i.e., the LCAT activity, and the LCAT concentration were significantly lower in sepsis compared to controls." (PMID 35071235, 2021). "LCAT ratio was significantly lower in sepsis compared to control (10.0 [8.0–11.8] vs. 15.3 [13.3–17.6], p < 0.0001)." (PMID 35071235, 2021). "Impaired LCAT activity in sepsis patients has been described before." (PMID 39051245, 2024). "Taken together, we provide specific data on the rapid and robust changes of HDL metabolism in sepsis, in which HDL particles accumulate pro-inflammatory SAA on one hand, and lose HDL-C content and HDL-metabolism associated proteins such as LCAT on the other hand." (PMID 35071235, 2021). "Recombinant LCAT may improve outcomes in these patients and may also provide a potential future drug in the armamentarium against sepsis." (PMID 35071235, 2021). "Therefore, we identified a potential intervention site at which regulating cholesterol and lecithin cholesterol acyltransferase might inhibit the progression of sepsis in the early stage." (PMID 36579569, 2022). "A decrease in plasma LPC was reported to be the result of an attenuated lecithin-cholesterol acyltransferase and secretory phospholipases A2 that was accompanied with an increase in LPCAT1-3 activity, suggesting that sepsis triggers LPC conversion to PC." (PMID 39369060, 2024). "LCAT activity, LCAT concentration and CETP activity were significantly lower, while PLTP activity was significantly higher in ICU sepsis compared to ICU control patients." (PMID 35071235, 2021). "Taken together, the increase in cholesterol biosynthesis, decrease in bile acid biosynthesis, and a lack of lecithin-cholesterol acyltransferase activity are likely responsible for elevated FC levels and FC/CE ratio in AlbCreSR-BIfl/fl mice in sepsis." (PMID 39510181, 2024). "In addition, ATP-binding cassette transporters, transforming lipid-poor apolipoprotein A1 into mature HDL, and lecithin-cholesterol acyltransferase (LCAT), converting free cholesterol to cholesterol esters, are also affected during sepsis." (PMID 38015312, 2023). "LCAT activity and concentration were correlated with HDL-phospholipid levels in our sepsis cohort." (PMID 35071235, 2021). "Interestingly, we observed that LCAT activity was more than 50% decreased in sepsis patients compared to patients without sepsis or bacteremia." (PMID 35071235, 2021).
ovarian carcinoma (11 papers, 2021 to 2024). A malignant neoplasm originating from the surface ovarian epithelium. "LCAT has been associated with breast cancer, ovarian cancer, and Hodgkin’s lymphoma." (PMID 36330335, 2022). "In contrast, LCAT levels are lower in the serum of colorectal cancer, liver cancer, and ovarian cancer patients, making it a potential biomarker." (PMID 38195525, 2024). "LCAT is a potential biomarker for various cancers, including ovarian cancer, breast cancer, colorectal cancer, and liver cancer." (PMID 36903601, 2023). "Signal intensities for the quantified proteins overall spanned approximately seven orders of magnitude and included several previously reported ovarian cancer marker candidates, such as HE4, MSLN, VCAM-1, CEA, CRP, PROZ, LCAT, and M-CSF." (PMID 36669591, 2023). "A combined model of insulin-like growth factor-binding protein-2 (IGFBP-2), lecithin cholesterol acyltransferase (LCAT), and CA125 outperformed CA125 detection alone for the earlier detection of ovarian cancer in terms of the sensitivity." (PMID 36233339, 2022). "Lecithin-cholesterol acyltransferase (LCAT) is an important gene that is correlated with poor prognosis in many cancers, such as ovarian cancer, Hodgkin lymphoma, and breast cancer." (PMID 34034705, 2021).
breast cancer (10 papers, 2021 to 2024). A primary or metastatic malignant neoplasm involving the breast. "In breast cancer, LCAT overexpression was demonstrated to be associated with the tumor grade and aggressiveness." (PMID 36494696, 2022). "In the study, comparative analysis of canine and human cases revealed that the plasma protein LCAT was found a biomarker for advanced breast cancer as well as mammary tumors undergoing metastasis." (PMID 37009802, 2023). "Plasma LCAT showed a decreased activity in colorectal cancer and breast cancer patients." (PMID 36588724, 2022). "Previous study found that LCAT was overexpressed in the sera of high-grade and lymph-node-positive breast cancer and could be a common plasma protein marker in aggressive breast cancer." (PMID 34336648, 2021).
hypertriglyceridemia (10 papers, 2009 to 2025). A laboratory test result indicating elevated triglyceride concentration in the blood. "LCAT: LCAT deficiency is an autosomal recessive condition characterized by severe hypoalphalipoproteinemia, hypertriglyceridemia, and corneal opacities." (PMID 40004987, 2025). "Furthermore, hypertriglyceridemia in CKD rats is associated with impaired maturation of HDL-3 to HDL-2 mediated by LCAT deficiency which further contributes to defective lipolysis and clearance of triglyceride-rich lipoproteins (i.e. VLDL and chylomicrons) in circulation." (PMID 31828139, 2019). "Therefore, it is unlikely that increased serum LCAT activity causes hypertriglyceridemia; instead, hypertriglyceridemia may facilitate LCAT activity." (PMID 30055622, 2018). "Heterozygous LCAT genetic loss-of-function variant carriers will have moderately lower HDL-C and moderate hypertriglyceridemia." (PMID 40004987, 2025). "Authors have not establish any relationships between plasma TG levels and dialysis duration, whereas others have found correlation between hypertriglyceridemia, cholesterol, lecithin-cholesterol acyltransferase (LCAT) activity and hemodialysis duration." (PMID 19709414, 2009). "Herein, we revealed that this hypertriglyceridemia could be partially reversed by fenofibrate treatment in LCAT KO hamsters." (PMID 41195480, 2025). "We have previously reported that hypertriglyceridemia occurred in LCAT KO hamsters." (PMID 41195480, 2025). "Compared with WT hamsters, LCAT KO hamsters on a chow diet presented hypertriglyceridemia, but the difference between fasted and refed states was not statistically significant." (PMID 41195480, 2025). "The in vivo results of the present study show that Tx patients with and without statin therapy had moderate hypertriglyceridemia, hypercholesterolemia, dyslipoproteinemia, and atherogenic lipid and lipoprotein ratios, decreased LCAT mass, and slightly increased hsCRP, but no CETP activity." (PMID 23479335, 2013). "Tx patients had moderate hypertriglyceridemia, hypercholesterolemia, and dyslipoproteinemia, disturbed triglyceride-rich lipoproteins (TRLs) and HDL composition, decreased LCAT, and slightly increased hsCRP but no CETP activity." (PMID 23479335, 2013).
hypoalphalipoproteinemia (10 papers, 2012 to 2025). A metabolic disorder characterized by deficiency of high density (alpha) lipoprotein in the blood. "Two rare mutations of LCAT gene, p.V333 M and p.M404 V, were identified in a Chilean patient with hypoalphalipoproteinemia, corneal opacity, mild anemia and other impaired lipid-related clinical traits." (PMID 31164121, 2019). "Genetic mutations in ABCA1, apoA-1, and LCAT are associated with familial hypoalphalipoproteinemia." (PMID 32455724, 2020). "The hypoalphalipoproteinemia associated with the high unesterified/total cholesterol ratio of the proband was suggestive of a defect in the cholesterol esterification process; thus, the analysis of LCAT gene was performed." (PMID 22658148, 2012). "We evaluated targeted, next-generation sequencing data from patients with very low levels of HDL cholesterol (i.e., hypoalphalipoproteinemia) with the VarSeq-CNV® caller algorithm to screen for CNVs that disrupted the ABCA1, LCAT, or APOA1 genes." (PMID 29866657, 2018). "CNVs disrupting ABCA1, APOA1, or LCAT in individuals with hypoalphalipoproteinemia have not yet been reported." (PMID 29866657, 2018).
liver cancer (10 papers, 2018 to 2025). An epithelial or non-epithelial malignant neoplasm that arises from the liver. "Long’s research suggested that LCAT was a protective gene and was associated with a favorable prognosis in liver cancer patients." (PMID 40533802, 2025). "Thus, we inferred that LCAT is primarily associated with liver cancer metastasis." (PMID 38195525, 2024). "Third, it demands more robust assays to explore the molecular mechanisms by which LCAT induces disulfidptosis, and to demonstrate that LCAT is capable of hindering liver cancer metastasis." (PMID 38195525, 2024). "Firstly, Western blotting analysis revealed that liver cancer cells expressed less of the LCAT protein than normal liver cells did." (PMID 38195525, 2024). "Ultimately, we demonstrated that a few hub DRGs have differential mRNA expression between liver cancer cells and normal cells and that the protective gene LCAT can inhibit liver cancer metastasis in vitro." (PMID 38195525, 2024). "Our experiments have confirmed the low expression of LCAT in liver cancer cell lines, consistent with previous reports." (PMID 38195525, 2024). "However, LCAT has a limited impact on the proliferation and colony formation abilities of liver cancer cells, suggesting that LCAT mainly affects the metastasis of liver cancer by inducing disulfidptosis." (PMID 38195525, 2024). "Additionally, models consisting of SPP1 and lecithin-cholesterol acyltransferase (LCAT) are good at predicting liver cancer diagnosis, prognosis and recurrence." (PMID 38374893, 2024). "Furthermore, in vitro experiments have clearly demonstrated that LCAT significantly inhibits the migration and invasion abilities of liver cancer cells, and promotes cell death via disulfide bond formation under glucose deprivation conditions." (PMID 38195525, 2024). "Additionally, we revealed the role of LCAT induced disulfidptosis in the progression of liver cancer, providing new insight into liver cancer treatment via targeted disulfidptosis." (PMID 38195525, 2024). "However, LCAT did little to suppressed the cell proliferation and colony formation capabilities of liver cancer cells in vitro." (PMID 38195525, 2024). "Of note, AKR1B10, ACSL4, GLS2, LCAT, were among the metabolic targets we previously identified as consistent in HCC, indicating a high alteration frequency of these genes across liver cancer datasets." (PMID 30176945, 2018).
Hypercholesterolemia (9 papers, 2013 to 2024). An increased concentration of cholesterol in the blood. "Considering hypercholesterolemia as a leading cause of MASLD, many natural products can attenuate hypercholesterolemia by upregulating LCAT and SR-BI expression and downregulating CEPT expression, thereby accelerating RCT." (PMID 39204178, 2024). "For example, one study found that LCAT expression levels were downregulated in some patients with hereditary hypercholesterolemia, possibly due to abnormal LCAT function due to genetic mutations." (PMID 37687178, 2023). "However, our previous studies using recombinant modified LCAT(C31Y) proteins in rabbits have provided proof-of-concept evidence that LCAT activation facilitates cholesterol mobilization, promotes RCT in vivo, and attenuates atherogenesis under high fat diet-induced hypercholesterolemia." (PMID 26644477, 2016).
liver cirrhosis (9 papers, 2010 to 2025). "Reduced HDL levels due to decreased hepatic lecithin-cholesterol acyltransferase (LCAT) activity in patients with liver cirrhosis associate with occurrence of relative adrenal insufficiency (RAI)." (PMID 40551885, 2025). "Two diagnostic models including SOCS2, LCAT, FTCD, KRT17, PBK, and CBX2 expression were proved to accurately separate HCC from normal and liver cirrhosis samples in this study." (PMID 36159831, 2022). "In addition, bioinformatics analysis has indicated that LCAT plays a critical role in the development of liver cirrhosis into HCC." (PMID 38195525, 2024). "LCAT is expressed in the liver and its activity is decreased in patients with liver cirrhosis." (PMID 36551908, 2022). "Serum CETP, PLTP and LCAT activities in control subjects and patients with liver cirrhosis." (PMID 20470383, 2010). "Notably, in liver cirrhosis, there is a significant decrease in LCAT enzyme activity." (PMID 39114211, 2024). "Besides, LCAT plays a crucial role in the conversion of liver cirrhosis into HCC." (PMID 35196258, 2022). "By integrating multiple microarray gene expression profiles, three key genes (LCAT, CYP2C9, and CDKN3) were identified that appear to be important for the conversion of liver cirrhosis into HCC." (PMID 32000807, 2020). "Decreased LCAT activity has been described in patients with liver cirrhosis, but whether ACAT2 activity is also low has not been clarified yet." (PMID 36551908, 2022).
type 2 diabetes (9 papers, 2014 to 2024). "Impaired LCAT activity is also associated with several other oxidative stress‐related diseases, such as cirrhosis, chronic liver disease, and type 2 diabetes, among others." (PMID 27033448, 2016). "This has intriguing implications for the mechanism of action of gliflozins, which are commonly used in the treatment of type 2 diabetes, and for the endogenous activation of LCAT." (PMID 39478139, 2024). "It was shown previously that LCAT activity is increased in patients suffering from type 2 diabetes and that it is supposedly connected to reduced anti-oxidative capacity of HDL." (PMID 33673728, 2021). "Specifically, subjects with an FLI ≥ 60 coinciding with type 2 diabetes mellitus (T2DM) and metabolic syndrome (MetS) exhibit an average 12% higher plasma LCAT activity." (PMID 39204178, 2024).
Hepatic steatosis (8 papers, 2016 to 2026). Steatosis is a term used to denote lipid accumulation within hepatocytes. "At present, we provide compelling evidence that LCAT plays a causal role in hepatic steatosis." (PMID 41195480, 2025). "The reduced levels of CHO potentially associated with reduced activity of LCAT may predispose animals to fatty liver disease." (PMID 39015111, 2024). "Because LCAT activity decreases in cows with fatty liver, it is considered to directly reflect this pathological condition." (PMID 39765544, 2024). "Alike, miR-26b-5p influences translation of caveolin 2 and diacylglycerol O-acyltransferase 1, i.e. a key enzyme in hepatic steatosis in addition to lecithin-cholesterol acyltransferase which catalyzes its esterification for cholesterol transport." (PMID 27045805, 2016). "In the present study, we used lipidomics via LC‒MS and clarified that LCAT deficiency promotes hepatic steatosis independent of HFHC diet challenge." (PMID 41195480, 2025). "Similarly to the NEFA concentration, this decrease was also indicative of fatty liver because reduced LCAT activity has been demonstrated in ethionine-induced fatty liver, as well as in naturally occurring hepatic lipidosis." (PMID 39765544, 2024). "Whether LCAT has a causal role in hepatic steatosis is not very clear." (PMID 41195480, 2025). "Researchers have not conclusively determined whether LCAT KO has a significant effect on liver steatosis in LCAT KO mice." (PMID 41195480, 2025).
Tangier disease (8 papers, 2007 to 2025). "Corneal opacification, the characteristic physical finding in LCAT deficiency state, is more severe than the accumulation of cholesterol in the cornea that can be sporadically seen in apoA-I deficiency and Tangier disease." (PMID 36651718, 2023). "Among patients with severely lowered HDL cholesterol, 2–3% have monogenic disorders (i.e. recessive Tangier disease, LCAT deficiency or apo A-I deficiency)." (PMID 32041611, 2020). "Genetic mutations in ABCA1 (Tangier disease), LCAT (familial lecithin:cholesterol acyltransferase deficiency), ApoA1 (familial apolipoprotein (Apo) A1 deficiency), and UBIAD1 (Schnyder corneal dystrophy, SCD) all result in corneal accumulation of lipids including cholesterol." (PMID 34547023, 2021). "With ABCA1 deficiency (i.e., Tangier disease), there is very mild corneal clouding (usually requiring a slit-lamp examination for its detection) and less abundant extracellular corneal stromal deposits, cholesterol, and phospholipid accumulation compared with genetic deficiency of LCAT." (PMID 31779197, 2019).
anemia (7 papers, 2016 to 2025). A reduction in the number of red blood cells, the amount of hemoglobin, and/or the volume of packed red blood cells. "Complete LCAT deficiency also leads to diffuse stromal opacification, along with renal disease and anemia." (PMID 40937252, 2025). "Familial LCAT deficiency leads to anemia due to accumulation of free cholesterol in red blood cells and to kidney failure." (PMID 35071235, 2021). "Compared with a normolipidemic cohort, patients with total deficiency of the FC-esterifying enzyme, lecithin-cholesterol acyltransferase, have a high FC/CE ratio and present with hemolytic anemia, in which there is premature erythrocyte hemolysis that results in anemia." (PMID 37821077, 2023). "Herein, we identified the rare p.V333 M and p.M404 V mutations in the LCAT gene as a cause of LCAT deficiency in a Chilean patient with very low plasma HDL-cholesterol levels, corneal opacity, mild anaemia and multiple impaired lipid-related traits." (PMID 31164121, 2019).
renal failure (7 papers, 2014 to 2024). "LCAT deficiency is an autosomal receive disease characterized by low HDL levels, and depending on the mutation of the LCAT gene, it can lead to premature corneal opacification, hemolytic anemia, proteinuria, and renal failure." (PMID 38355710, 2024). "The major clinical complication observed in LCAT deficient subjects is kidney dysfunction; carriers often present with proteinuria very early in life, and they usually develop renal failure with symptomatic edema and hypertension during the third-fourth decade of life." (PMID 32708515, 2020). "In FLD, both the alpha and beta LCAT activity is lost and result in extremely low serum HDL levels, the premature corneal opacification, hemolytic anemia, proteinuria and renal failure." (PMID 36588724, 2022).
Cirrhosis (6 papers, 2016 to 2025). A chronic disorder of the liver in which liver tissue becomes scarred and is partially replaced by regenerative nodules and fibrotic tissue resulting in loss of liver function. "Patients with cirrhotic end-stage liver disease have lower levels of circulating LCAT, besides alterations in CETP and HL activities, which raises the possibility that defective lipoprotein remodeling and catabolism may contribute to the generation of LP-Z in cirrhosis." (PMID 35268313, 2022).